PPARGC1A (PPARG coactivator 1 alpha)
Diseases named in the same sentence as PPARGC1A in open-access papers (continued):
Sharing a sentence is not in itself a finding about the gene and the disease.
colorectal cancer (24 papers, 2017 to 2025). A primary or metastatic malignant neoplasm that affects the colon or rectum. "In another study, genetic polymorphisms in PPARGC1A (rs3774921) increased the risk of colorectal cancer in individuals fed a highly inflammatory diet." (PMID 34322151, 2021). "In our study, we observed a significantly stronger association for a pro-inflammatory diet with the risk of colorectal cancer among those harboring the rs3774921 homozygous variant allele of PPARGC1A compared to those carrying the wild-type allele." (PMID 28051997, 2017). "We found that the association between DII score and colorectal cancer risk differed according to the genetic variant of PPARGC1A." (PMID 28051997, 2017). "Among the investigated polymorphisms, an association with a higher risk of colorectal cancer was observed for heterozygous carriers of rs3774921 in the PPARGC1A (OR [95% CI] = 1.26 [1.02–1.55] for TC vs. TT)." (PMID 28051997, 2017). "Among the polymorphisms investigated in the present study, only the PPARGC1A variant appears to be associated with the risk of colorectal cancer." (PMID 28051997, 2017). "Among the investigated polymorphisms, heterozygous carriers of rs3774921 in PPARGC1A showed a higher risk of colorectal cancer (OR [95% CI] = 1.26 [1.02–1.55] for TC vs. TT)." (PMID 28051997, 2017). "In the present study, carriers of a particular PPARGC1A genetic variant exhibited an increased risk of colorectal cancer." (PMID 28051997, 2017). "Similarly, in a case-control study on 701 colorectal cancer patients, a polymorphism (rs3774921) in the PPARGC1A gene was associated with a higher risk of colorectal cancer, and more so in combination with a pro-inflammatory diet." (PMID 29361779, 2018). "In conclusion, the results of this study suggest that a pro-inflammatory diet may have a differential effect on colorectal cancer risk based on PPARGC1A genetic variation." (PMID 28051997, 2017). "In conclusion, a pro-inflammatory diet may increase the risk of colorectal cancer, particularly among those with genetic variation in the PPARGC1A gene." (PMID 28051997, 2017). "We also examined whether the interaction between PPARGC1A genetic variation and diet-associated inflammation in relation to colorectal cancer risk could be modified by other risk factors such as age, BMI, regular exercise, and smoking status." (PMID 28051997, 2017). "PGC-1a (encoded by PPARGC1A) is a master of OXPHOS and has been proved to promote chemoresistance and stemness in colorectal cancer 21,23." (PMID 37771767, 2023). "We genotyped four polymorphisms in four genes (IL1B, TNF, PPARG, and PPARGC1A) and calculated the dietary inflammatory index (DII) in a case-control study with 701 colorectal cancer patients and 1,402 controls." (PMID 28051997, 2017). "However, the effect of PPARGC1A on the initiation and progression of colorectal cancer remains controversial." (PMID 34322151, 2021). "Interaction between the PPARGC1A rs3774921 genotype and DII score in relation to colorectal cancer risk was much stronger among those who were older than 50 years (P for interaction = 0.005), were not overweight (P for interaction = 0.03), and did not exercise regularly (P for interaction = 0.004)." (PMID 28051997, 2017). "Ppargc1a (also known as Pgc1α) is a transcriptional regulator of mitochondrial biogenesis and oxidative phosphorylation in which its reduced expression in cancers including colorectal cancer (CRC) has previously been suggested to contribute to the Warburg effect." (PMID 29339782, 2018).
liver cancer (24 papers, 2015 to 2025). An epithelial or non-epithelial malignant neoplasm that arises from the liver. "PPARGC1A has also been shown to be closely associated with liver cancer and other related metabolic diseases." (PMID 40564032, 2025). "Tumor-associated macrophages (TAMs) and tumor microenvironments (TME s) are key drivers of hepatocarcinogenesis and progression, and PPARGC1A has been identified as a TAM-associated prognostic genes in liver cancer." (PMID 40564032, 2025). "In our results, S100A9, SLC22A15, TRIM54, and PPARGC1A were identified as TIMGs, which were identified as prognostic biomarkers for liver cancer sufferers." (PMID 36120553, 2022). "PPARGC1A is a mitochondrial regulator, which can regulate mitochondrial biogenesis in macrophages and play a regulatory role in the growth and metastasis of liver cancer." (PMID 36120553, 2022). "To date, studies on S100A9 and PPARGC1A have been suggested as a new potential biomarker for liver cancer." (PMID 36120553, 2022). "Overall, S100A9, SLC22A15, TRIM54, and PPARGC1A were screened as TIMGs that can be used for prognostic prediction and be the potential targets of the ICI treatments for patients with liver cancer." (PMID 36120553, 2022). "PPARGC1A and SOCS2 are considered to be tumor suppressors in liver cancer, while SLC25A members are involved in mitochondrial Ca2+ signaling important for hepatocyte physiology." (PMID 30867900, 2019). "Using The Cancer Genome Atlas datasets to re-analyze the effect of some previously reported metastatic genes-e.g., JAM2, PPARGC1A, SIK2, and TRAF6-on overall survival of patients with renal and liver cancers, we found that these genes are actually protective factors for patients with cancer." (PMID 28372569, 2017). "No study has hitherto studied the role of PPARGC1A in liver cancer, warranting further studies." (PMID 35517787, 2022). "Additionally, targeting PPARGC1A, a key regulator of mitochondrial biogenesis and energy metabolism, with PPAR agonists such as fenofibrate could mitigate PFAS-induced metabolic reprogramming in liver cancer cells." (PMID 40317014, 2025).
Glucose intolerance (23 papers, 2011 to 2025). Glucose intolerance (GI) can be defined as dysglycemia that comprises both prediabetes and diabetes. "Although altered expression of Ppargc1a mRNA in skeletal muscle might be one of causes improve the glucose intolerance in middle-aged mice, the results of the present study showed no changes between Control and High fat groups at 13-mo-old." (PMID 32793459, 2020). "This diet also caused a deficient hippocampus-dependent performance, increased locomotion, downregulated mitochondrial activity marker PPARGC1a in the brain but not in the liver, and induced glucose intolerance and hyperleptin/hypercholesterolemia in mice." (PMID 28685102, 2017).
pancreatic cancer (20 papers, 2014 to 2024). "Furthermore, PPARGC1A upregulation has been shown as a determinant of cancer stem cell dependency on oxidative metabolism in pancreatic cancer." (PMID 34206049, 2021). "PPARGC1A was found to be elevated in CTCs from a variety of experimental models, and has been shown to play a role in oxidative phosphorylation in breast and pancreatic cancer cells, helping them meet their growing demand for energy as they proliferate rapidly." (PMID 34206049, 2021).
chronic kidney disease (19 papers, 2013 to 2025). Impairment of the renal function secondary to chronic kidney damage persisting for three or more months. "Hes1 was reported to bind directly to the Ppargc1a promoter region and inhibit PGC-1α expression in animal models of chronic kidney disease (CKD)." (PMID 35225153, 2022). "TGFβ suppresses the PPARA’s expression in chronic kidney disease (CKD) patients with kidney fibrosis and our in vitro and in vivo studies showed that PPARA or PPARGC1A was down-regulated by zoledronate treatments." (PMID 28871336, 2018).
liver fibrosis (19 papers, 2015 to 2025). "Liver fibrosis and impaired PPARGC1A activity are associated with non-alcoholic fatty liver diseases." (PMID 33133155, 2020). "Importantly, PPARGC1A-knockout mice challenged with CCL4 or a high-fat diet presented abnormal mitochondrial fission, increased oxidative stress, and more severe liver fibrosis than wild-type mice." (PMID 37296834, 2023). "The increased hepatic levels of Ppargc1a in TKO-HFD mice may counteract the effect of IL-1β through increased anti-inflammatory signaling, suggesting that TKO mice may also be protected against hepatic fibrosis." (PMID 26168159, 2015).
lung fibrosis (18 papers, 2018 to 2025). "Recently, the increased expression of Dio2 and decreased expression of Ppargc1a (peroxisome proliferator-activated receptor gamma coactivator 1-alpha), a master regulator of mitochondrial biogenesis, had been shown in a mouse model of refractory lung disease, idiopathic pulmonary fibrosis (IPF)." (PMID 38247455, 2023).
gastric cancer (15 papers, 2018 to 2025). A primary or metastatic malignant neoplasm involving the stomach. "In addition, a Chinese population-based study has revealed that the single-nucleotide variants of PPARγ, PPARGC1A, and PPARGC1B may be related to the susceptibility factors of gastric cancer in an eastern Chinese population." (PMID 38495486, 2024). "The purpose of this study was to investigate the association of PPARγ, PPARGC1A, and PPARGC1B variants with the risk of gastric cancer (GC)." (PMID 36587194, 2022).
non-small cell lung carcinoma (15 papers, 2020 to 2025). A group of at least three distinct histological types of lung cancer, including non-small cell squamous cell carcinoma, adenocarcinoma, and large cell carcinoma. "In contrast, PPARGC1A is over-expressed in non-small-cell lung cancer, where it actively promotes metastatic dissemination." (PMID 40564032, 2025).
osteoporosis (13 papers, 2019 to 2026). A condition of reduced bone mass, with decreased cortical thickness and a decrease in the number and size of the trabeculae of cancellous bone (but normal chemical composition), resulting in increased fracture incidence. "Our study objective was to examine the relationship between PPARγ and PPARGC1A polymorphisms and the development of BRONJ in patients with osteoporosis patients undergoing bisphosphonate treatment." (PMID 37513946, 2023). "This study aimed to examine the relationship between PPARγ and PPARGC1A polymorphisms and the BRONJ development in female osteoporosis patients undergoing bisphosphonate treatment." (PMID 37513946, 2023). "In this study, our objective was to investigate the association between PPARγ and PPARGC1A polymorphisms and the development of BRONJ in osteoporosis patients undergoing bisphosphonate treatment." (PMID 37513946, 2023).
clear cell renal cell carcinoma (11 papers, 2018 to 2026). "However, the link between increased PPARGC1A expression and a favorable prognosis in clear cell renal cell carcinoma remains contentious." (PMID 37903487, 2024).
schizophrenia (11 papers, 2013 to 2024). A major psychotic disorder characterized by abnormalities in the perception or expression of reality. "PPARGC1A has been recognized as a leading candidate gene for schizophrenia (SCZ) through genome-wide association studies, and has been found to play a role in the postnatal brain development in individuals with SCZ59." (PMID 39019913, 2024). "In fact, the chromosomal location including PPARGC1A has been linked to risk for schizophrenia and bipolar disorder, and a recent genome-wide association study found a significant association between schizophrenia and rs215411, a single-nucleotide polymorphism ~370 kb downstream of PPARGC1A." (PMID 33572179, 2021).
Impaired glucose tolerance (10 papers, 2009 to 2025). An abnormal resistance to glucose, i.e., a reduction in the ability to maintain glucose levels in the blood stream within normal limits following oral or intravenous administration of glucose. "Increased PPARGC1A promoter methylation has also been reported in skeletal muscle from individuals with impaired glucose tolerance (IGT) and T2D in a more proximal region of the PPARGC1A promoter located 337-37 bp upstream from the transcription start." (PMID 23505498, 2013).
kidney damage (9 papers, 2017 to 2025). "While functions for Ppargc1a in vertebrate renal development have not been reported until the present study, interesting roles of PGC-1α have been identified during the response to kidney damage in mammals." (PMID 30475208, 2018).
osteosarcoma (9 papers, 2019 to 2025). A usually aggressive malignant bone-forming mesenchymal neoplasm, predominantly affecting adolescents and young adults. "When investigating the expression of PPARGC1A, in the samples Ch-P4, L-P5, and Rm-P6, treatments with AA bFGF and DHA bFGF lead to an increase in its expression, while this effect is not observed in osteosarcomas." (PMID 41300532, 2025).
age-related macular degeneration (8 papers, 2013 to 2022). Age-related loss of vision in the central portion of the retina (macula), secondary to retinal degeneration. "We have linked the co-activator of a lipid-sensing transcription factor (PPARG co-activator 1 alpha, PPARGC1A) to age-related macular degeneration (AMD) and AMD-associated genes." (PMID 23335958, 2013). "We postulated that DNA sequence variation in PPAR gamma (PPARG) co-activator 1 alpha (PPARGC1A), a gene encoding a co-activator of the LCPUFA-sensing PPARG-retinoid X receptor (RXR) transcription complex, may influence neovascularization (NV) in age-related macular degeneration (AMD)." (PMID 23335958, 2013).
COVID-19 (7 papers, 2021 to 2025). A disease caused by infection with severe acute respiratory syndrome coronavirus 2. "Based on this background, the present study is set to investigate the roles of the ACE rs4646994, ACTN3 rs1815739, and PPARGC1A rs8192678 polymorphisms in determining the severity of COVID-19 outcomes." (PMID 40150043, 2025). "In terms of combined genetic effects, polymorphisms in ACE, ACTN3, and PPARGC1A likely interact to influence COVID-19 outcomes." (PMID 40150043, 2025). "The effects of ACE1 rs4646994, PPARGC1A rs8192678, and ACTN3 rs1815739 polymorphisms on COVID-19 severity were evaluated." (PMID 40150043, 2025). "Our study showed that the expression of mitochondrion-encoding genes was upregulated and that of the mitochondrial biogenesis–related gene PPARGC1A (PGC-1α) was downregulated in the alveolar epithelial cells of patients with COVID-19." (PMID 35844544, 2022). "Seven common DEGs (PPARGC1A, FUBP1, ITGB8, SYCP2, RSAD2, FGF1, and FERMT1) were identified from the GSE164805 dataset of patients with mild COVID-19, and the GSE50395 dataset from APS patients." (PMID 36241659, 2022).
liver disease (7 papers, 2019 to 2025). "However, TSG’s hepatotoxic effects are manifested through the inhibition of PPARGC1A and PPARγ expression, thereby activating the NF-κB and STAT signaling pathways, commonly dysregulated in liver diseases and potentially leading to LI." (PMID 39963244, 2025).
energy metabolism disorder (6 papers, 2015 to 2026). "RPS21 may regulate PPARGC1A expression by interacting with hsa-mir-193b-3p, thereby influencing mitochondrial biogenesis and autophagy, contributing to energy metabolism disorder in retinal cells and playing a role in DR progression." (PMID 41601931, 2026).
lung adenocarcinoma (6 papers, 2018 to 2025). A carcinoma that arises from the lung and is characterized by the presence of malignant glandular epithelial cells. "Using canonical circuit activity analysis, we discovered PPARGC1A, which encodes the protein PGC1α, as significantly upregulated in KRASHigh/LKB1Mut lung adenocarcinoma patients." (PMID 33514834, 2021). "The CancerMIRNome analysis shows the miR‐485‐3p and PPARGC1A expression low‐correlation in lung adenocarcinoma tissues." (PMID 40788065, 2025).
prostate tumor (5 papers, 2018 to 2025). "Compelling evidence suggests that PPARGC1A may play a dual role in promoting and inhibiting the development of prostate tumors under certain conditions." (PMID 39524226, 2024).
intervertebral disc degeneration (4 papers, 2022 to 2025). "In the process of intervertebral disc degeneration, PPARGC1A has been proven to protect annulus fibrosus cells against apoptosis under oxidative stress." (PMID 37234868, 2023).
rhabdomyosarcoma (4 papers, 2012 to 2025). A rare aggressive malignant mesenchymal neoplasm arising from skeletal muscle. "Expression analysis of PPARGC1A, encoding the mitochondrial biogenesis regulator PGC-1α and indicative of a metabolic shift toward oxidative phosphorylation, demonstrated upregulation in cancer stem cells derived from liposarcoma and rhabdomyosarcoma." (PMID 41300532, 2025). "A significant increase of PPARGC1A and FNDC5 mRNA abundance was noticed in cultured human rhabdomyosarcoma cells after treatment with a combination of omega-3 fatty acids for 24 or 48 hours." (PMID 24498244, 2014).
autism (3 papers, 2016 to 2024). Persistent deficits in social interaction and communication and interaction as well as a markedly restricted repertoire of activity and interest as well as repetitive patterns of behavior. "Mice genetically lacking the PPARGC1a gene exhibited an imbalance between inhibitory and excitatory synaptic transmission in the hippocampus, a mechanism that is suggested to be an important pathogenetic factor of autism." (PMID 28685102, 2017). "Mice genetically lacking the PPARGC1a gene exhibit an imbalance between inhibitory and excitatory synaptic transmission in the hippocampus, a mechanism that is suggested to be an important pathogenetic factor of autism." (PMID 28685102, 2017).
hypothyroidism (3 papers, 2015 to 2022). Abnormally low levels of thyroid hormone. "Interestingly, MAT volume also tended to be lower with hypothyroidism; nevertheless, the mRNA expression profile only showed a decrease in Ppargc1a transcript levels, the master regulator of mitochondrial biogenesis." (PMID 36143246, 2022). "In BAT, we found reduced Klf9 (−34.82%) expression and 2.51-fold increased mRNA levels of Ucp1, the master regulator of brown adipocyte thermogenesis, although Prdm16, the transcriptional coregulator of brown adipocyte differentiation, and Ppargc1a were not regulated by hypothyroidism." (PMID 36143246, 2022).
oral cancer (3 papers, 2023 to 2025). "Our study showed that CLU and PPARGC1A coordinately regulate mitophagy and biogenesis to enhance cell survival in oral cancer during cisplatin treatment." (PMID 38447939, 2024). "To establish the correlation between CLU and PPARGC1A in regulating mitochondrial functionality, we measured the alteration in their expression in oral cancer cells." (PMID 38447939, 2024). "Our results confirm the idea that PPARGC1A inhibition enhanced cisplatin-induced mitochondrial dysfunction, which triggers mitochondrial (mt)ROS-dependent apoptosis in oral cancer cells." (PMID 38447939, 2024). "Pharmacological inhibition of PPARGC1A combined with cisplatin disturbed the balance between mitophagy and mitochondrial biogenesis, leading to excessive mitophagy, showing a potent synergistic effect in in vitro and in vivo models of oral cancer." (PMID 38447939, 2024). "We suggest that CLU and PPARGC1A are indispensable for controlling mitochondrial content during chemotherapeutic stress and that modulating their activity could strongly influence therapeutic responses in oral cancer." (PMID 38447939, 2024). "In conclusion, CLU and PPARGC1A are essential for sustained cancer cell growth by activating mitophagy and mitochondrial biogenesis, respectively, and their inhibition could provide better therapeutic benefits against oral cancer." (PMID 38447939, 2024).
porphyria (3 papers, 2014 to 2021). Porphyria is a group of diseases in which substances called porphyrins build up, negatively affecting the skin or nervous system. "Hepatic PPARGC1A and consequently ALAS1 are upregulated by diet restriction and such a response is implicated in the precipitation of acute porphyria attacks in fasting susceptible patients." (PMID 34900592, 2021).